ZNF204P (zinc finger protein 204, pseudogene)
Synonyms: b24o18.1; ZNF184-Lp; formerly ZNF204; ZNF315P
Gene: Transcribed unprocessed pseudogene on chromosome 6 (27,358,252 to 27,359,854, reverse strand). Ensembl gene ENSG00000204789.
Diseases named in the same sentence as ZNF204P in open-access papers:
ZNF204P is named in the same sentence as 2 diseases in open-access papers, as found by Europe PMC text mining. Sharing a sentence is not in itself a finding about the gene and the disease. The quoted sentences say what the papers report.
acute appendicitis (1 paper, 2025). "Finally, we defined three shared genes: PRSS16, ZNF602P, and ZNF204P by TWAS and nine pleiotropic genes C4A, FLOT1, LINC00243, MICB, and PRSS16 by colocalization analysis between MDD and acute appendicitis." (PMID 41438618, 2025). "Furthermore, we found that MDD and acute appendicitis have three shared genes: PRSS16, ZNF602P, and ZNF204P." (PMID 41438618, 2025). "We identified three shared genes—PRSS16, ZNF602P, and ZNF204P—between MDD and acute appendicitis." (PMID 41438618, 2025).
hepatocellular carcinoma (1 paper, 2026). A malignant tumor that arises from hepatocytes. "They show that as a decoy for tumor-suppressive miRNA-145-5p, ZNF204P interferes with the expression of OCT4 and SOX2, two regulators of pluripotency and self-renewal, and thereby plays an oncogenic stemness-associated role in hepatocellular carcinoma." (PMID 41431719, 2026). "Bioinformatic analysis revealed that, compared with normal tissue, ZNF204P (zinc finger protein 204, pseudogene) is expressed at a higher level in hepatocellular carcinoma samples, conferring a poor prognosis as well as enhanced stem cell preservation and proliferation." (PMID 41431719, 2026).